MRPS17 (mitochondrial ribosomal protein S17)
Synonyms: MRP-S17; S17mt; RPMS17; HSPC011; uS17m
Tractability: Small molecule: a structure with a bound ligand is known. PROTAC: ubiquitination databases record sites on it; its protein half-life has been measured.
Target class: Other cytosolic protein
Gene: Protein-coding gene on chromosome 7 (55,950,705 to 55,956,500, forward strand). Ensembl gene ENSG00000239789.
Subcellular location: Mitochondrion
Pathways (Reactome):
Metabolism of proteins: Mitochondrial ribosome-associated quality control; Mitochondrial translation elongation; Mitochondrial translation initiation; Mitochondrial translation termination
Gene Ontology:
Molecular function: protein binding; structural constituent of ribosome
Biological process: mitochondrial translation; translation
Cellular component: mitochondrial small ribosomal subunit; mitochondrion; mitochondrial inner membrane; ribosome
Genetic constraint (gnomAD): Loss-of-function variants: 6 observed, 11.87 expected, observed/expected ratio (o/e) 0.51, 90% interval 0.28 to 1. The upper end of that interval is the gene's LOEUF score, 1, which puts it in group 4 of 6, group 1 being the genes least tolerant of losing a copy. Missense variants: 139 observed, 161.91 expected, observed/expected ratio (o/e) 0.86, 90% interval 0.75 to 0.99. Synonymous variants: 56 observed, 62.99 expected, observed/expected ratio (o/e) 0.89, 90% interval 0.72 to 1.11.
Homologues: Orthologues: chimpanzee MRPS17 (99% identical), macaque MRPS17 (99% identical), dog MRPS17 (88% identical), rat Mrps17 (82% identical), mouse Mrps17 (80% identical), zebrafish mrps17 (72% identical), tropical clawed frog mrps17 (68% identical), Drosophila melanogaster mRpS17 (31% identical), Caenorhabditis elegans mrps-17 (29% identical).
Diseases named in the same sentence as MRPS17 in open-access papers:
MRPS17 is named in the same sentence as 8 diseases in open-access papers, as found by Europe PMC text mining. Sharing a sentence is not in itself a finding about the gene and the disease. The quoted sentences say what the papers report.
gastric cancer (5 papers, 2021 to 2025). A primary or metastatic malignant neoplasm involving the stomach. "High MRPS17 expression was associated with a worse prognosis in gastric cancer patients." (PMID 39859078, 2025). "As for the collagen-containing extracellular matrix, Zhou’s study showed that Mitochondrial Ribosomal Protein S17 (MRPS17) can promote tumor cell metastasis through this pathway in gastric cancer." (PMID 36980973, 2023). "In the data sample set of 413 people gastric cancer samples and 34 normal gastric tissues, the expression of MRPS17 in gastric cancer increased significantly." (PMID 34234855, 2021). "We further used tissue samples from the HPA database to observe the public results of MRPS17 immunohistochemical detection related experiments and found that MRPS17 is highly expressed in gastric cancer tissues." (PMID 34234855, 2021). "Correlation analysis showed that patients diagnosed with T3-4 gastric cancer had high expression of MRPS17 (P<0.001), suggesting that MRPS17 is more likely to be highly expressed in advanced or aggressive gastric cancer." (PMID 34234855, 2021). "In order to determine if the MRPS17 is different between gastric cancer and normal tissue, we first analyzed the gene sequencing data results of all gastric cancer tumor tissue specimens in the TCGA database." (PMID 34234855, 2021). "Additionally, the expression levels of MRPS17 are also typically higher in gastric cancer tissues than in normal tissues." (PMID 40371222, 2025). "MRPS17 is upregulated in many types of cancer, including gastric cancer." (PMID 39859078, 2025). "Furthermore, a more recent human study has revealed that MRPS17 promotes gastric cancer metastasis through abnormal signaling of phosphatidylinositol-3 kinase/Akt (PI3K/Akt), a pathway commonly dysregulated in NSCLC." (PMID 36067173, 2022). "We found that MRPS17 is expressed in both nucleus and cytoplasm, and compared with normal gastric cell lines, MRPS17 has a higher nuclear protein expression in gastric cancer cell lines, suggesting the potentially important role of MRPS17 in the progression of gastric cancer cells." (PMID 34234855, 2021). "A follow-up study of 100 gastric cancer patients showed that patients with positive MRPS17 expression had a significantly worse prognosis than those with negative expression, and high MRPS17 expression, as an independent prognostic factor, was closely related to the aggressiveness of gastric cancer." (PMID 40371222, 2025). "In this study, the molecular mechanisms through which Mitochondrial Ribosomal Protein S17 (MRPS17) contributes to gastric cancer (GC) and its prognostic significance in GC have been explored." (PMID 34234855, 2021).
gastric adenocarcinoma (2 papers, 2021 to 2025). "Another study also demonstrated that high expression levels of MRPS17 are significantly associated with OS and RFS in patients with gastric adenocarcinoma." (PMID 40371222, 2025). "In gastric adenocarcinoma, the expression of MRPS17 is significantly negatively correlated with the abundance of TILs, indicating that high expression of MRPS17 may reduce immune cell infiltration and further influence immune evasion mechanisms." (PMID 40371222, 2025). "As a potential RNA binding protein, the specific function and molecular mechanism of MRPS17 in gastric adenocarcinoma have not been fully explored." (PMID 34234855, 2021).
glioma (2 papers, 2010 to 2021). A benign or malignant brain and spinal cord tumor that arises from glial cells (astrocytes, oligodendrocytes, ependymal cells). "Additionally, activation of PI3K/AKT pathway is responsible for malignant progression of glioma that was promoted by MRPS17." (PMID 34234855, 2021). "The expression of 5 genes (VSTM2A, SEPT14, MRPS17, PSPH and CCT6A) was undetectable in all these gliomas, regardless of their amplification status." (PMID 21170331, 2010).
cancer (5 papers, 2021 to 2025). A tumor composed of atypical neoplastic, often pleomorphic cells that invade other tissues. "The upregulation of MRPS17 has been linked with resistance to chemotherapy treatment as described in trials with anti-cancer agents, temozolomide and nitrosoureas." (PMID 36067173, 2022). "Among the hypoxia-related molecules, MRPS17, CDCHD2, PSMA7, and MIF consistently demonstrated a positive correlation with PEBP1/STK11 co-expression across all cancer types in which a significant association was observed." (PMID 40806276, 2025). "As we can see from the figure, the expression level of MRPS17 in cancer tissue (T) is generally higher than that in normal tissue (N)." (PMID 34234855, 2021). "MRPS17 is another gene that is consistently expressed in multiple cancers, including NSCLC." (PMID 36067173, 2022). "The specific roles and molecular mechanisms of MRPS17 in cancers remain ambiguous." (PMID 34234855, 2021). "Upregulated MRPS17, along with the elevated expression of other MRPs, enhances OXPHOS in cancer cells, thereby fueling cancer metabolism." (PMID 39859078, 2025). "MRPS17 and several gene signatures containing MRPs such as MRPL37, MRPS34, and MRPL11 may be independent indicators for cancer patients treated with chemotherapy or chemoradiotherapy." (PMID 39859078, 2025).
tumor (4 papers, 2010 to 2023). "Eight genes centromeric to SEPT14 (ZNF713, MRPS17, GBAS, PSPH, CCT6A, SUMF2, PHKG1 and CHCHD2) were amplified in tumour 4 only." (PMID 21170331, 2010).
MRPS17 also shares sentences with these, for which no sentence is quoted: asthma (1 paper); microcephaly (1); osteosarcoma (1).